TGFB1 (transforming growth factor beta 1)
Diseases named in the same sentence as TGFB1 in open-access papers (continued):
Sharing a sentence is not in itself a finding about the gene and the disease.
cardiac hypertrophy (272 papers, 2008 to 2026). "Interestingly, some of these targets such as Tgfb1, Hras, Fgf2, and Ppargc1a have been implicated in cardiac hypertrophy suggesting that low-dose dasatinib indeed impacts genes that affect heart growth and remodeling." (PMID 33689087, 2022). "Previous studies targeting TGFβ1 or TGFβR1 in cardiomyocytes have shown only modest improvements in cardiac fibrosis, with minimal reduction in ventricular dysfunction or myocardial hypertrophy." (PMID 39346544, 2024). "Recently, SCUBE3 was found to be involved in cardiac hypertrophy in mice through TGFβ1-mediated transcriptional activation." (PMID 34980127, 2022). "Early studies have found that SCUBE3 can participate in cardiac hypertrophy in mice through transcriptional activation mediated by TGFβ1." (PMID 34980127, 2022). "Specifically, numerous studies indicated that increased TGFβ1 expression plays an important role in heart hypertrophy, cardiac fibrosis, and cardiomyocyte apoptosis." (PMID 33195446, 2020). "TGFβ1 transgenic mice develop cardiac hypertrophy and interstitial fibrosis already under baseline conditions." (PMID 30895179, 2019). "TGFβ1 is upregulated in various experimental models of cardiac hypertrophy, and functional blockade of TGFβ1 prevents cardiac interstitial fibrosis induced by pressure overload in rats." (PMID 29941001, 2018). "Upregulation of TGFβ1 is also known to induce myocardial hypertrophy and is evident in animal models of heart failure." (PMID 28720711, 2017). "As the thin-walled RV dilates in the setting of pressure overload, increased RV wall stress activates signaling cascades that promote cardiac hypertrophy and fibrosis including the transforming growth factor beta-1 (TGFβ1) and calcineurin pathways." (PMID 23936252, 2013). "Hypoxia may induce the expression of TGFβ1, and increased expression levels of TGFβ1 have been observed during pathological cardiac hypertrophy remodeling including TAC and angiotensin II or isoproteronol stimulation." (PMID 30895179, 2019). "Treatment with a subpressor dose of Ang II does not induce cardiac hypertrophy or fibrosis in Tgfb1-deficient mice." (PMID 29259712, 2017). "However, the AT1 receptor blockade is insufficient to prevent the hypertrophic response in TGFβ transgenic mice, and TGFβ1 knockout mice are resistant to AngII-induced cardiac hypertrophy." (PMID 28509980, 2015). "Interestingly, this TGFβ1-induced cardiac hypertrophy is associated with increased myocardial β-adrenergic receptors (ARs) density and β-AR blockade treatment in TGFβ1 transgenic mice prevents cardiac hypertrophy." (PMID 28509980, 2015). "Some studies have indicated that TGFβ1 can activate TAK1 through the TGFBR1/2 complex, with activated TAK1 promoting cardiac hypertrophy via the p38/MAPK-JNK1/2 signaling pathway." (PMID 40880411, 2025). "Several studies have suggested that Tgfb1 increases ECM protein production and heart hypertrophy in response to Ang II through a mechanism involving Spp1, Serpine1, and Sparc." (PMID 36547406, 2022). "We also measured levels of growth factor β-1 (TGFβ-1) and vascular endothelial growth factor (VEGF), which have demonstrated roles in fibrosis and angiogenesis in the setting of cardiac hypertrophy." (PMID 22916095, 2012). "MicroRNA-21 (miR-21), transforming growth factor beta-1 (TGFβ-1), and Jagged1 (JAG1) were evaluated to determine whether conditions of cardiac hypertrophy and the MTS system can mediate gene expression in cardiac fibroblasts." (PMID 32867131, 2020). "Understanding the role of LRG1 in TGFβ1 and IGF1 interactions may shed new light on the molecular mechanism of cardiac hypertrophy." (PMID 28509980, 2015). "Unlike TGFβ1, it is unclear whether increased FN1 expression is a mechanism or consequence of fibrosis; however, it has been shown in transgenic animals that systemic FN1 knockout prevents pressure-overload induced cardiac hypertrophy and fibrosis." (PMID 31920673, 2019).
liver cancer (264 papers, 2007 to 2026). An epithelial or non-epithelial malignant neoplasm that arises from the liver. "Here we report a new species-dependent miRNA signalling mechanism and propose that switch of miR-122 target from TGFβR1 to TGFβ1 underlies the different patterns of liver cancer metastasis between the two species." (PMID 26987776, 2016). "In conclusion, our study shows that HNF1α loss can lead to epithelial-mesenchymal transition in liver cancer cell lines, with E-cadherin repression, TGFβ1 overexpression and increased migration abilities." (PMID 21975049, 2011). "For instance, HSD17B6 prevents liver cancer cell growth, migration, and invasion by regulating the expression of TGFB1." (PMID 38725005, 2024). "This study aims to assess the risk of developing hepatic cancer in HCV-infected patients due to the presence of IL-6–174 G/C and TGFβ-1 +29 C/T polymorphisms." (PMID 36215278, 2022). "pylori produce VacA and CagA in the HCC positive liver which promotes the growth of liver cancer.It also produces LPS that directly promotes the growth of liver cancer by elevating the level of TGFβ1 and IL8." (PMID 32405173, 2020). "Experimental switch of the miR-122 target between the receptor TGFβR1 and the ligand TGFβ1 changes the metastatic properties of mouse and human liver cancer cells." (PMID 26987776, 2016). "Western blot assay showed that the level of TGFβ1 was upregulated approximately four times in 11 liver cancer samples, whereas TGFβR1 expression remained moderate decrease." (PMID 26987776, 2016). "Recent study also demonstrated that lncRNA-ATB is induced by long-term TGFβ1 treatment, promoting liver cancer cell migration and invasion." (PMID 26152796, 2015). "LncRNA-ATB has been identified as overexpressed transcript in liver cancer cells with long term TGFβ1 treatment." (PMID 26152796, 2015). "With pbMOO approach, a new pathway “TGFβ1- TGFβR1- AR-OCIAD2” in liver cancer mesenchymal stem cell was predicted, which will differentiate into Tumor-Associated-Fibroblasts (TAFs), one of the major components of tumor stroma." (PMID 24949437, 2014). "Moreover, we validated the expression of HILPDA and the correlation between the expression of HILPDA and TGFB1/CD274 using 13 paired samples from liver cancer patients." (PMID 33816230, 2021). "Moreover, we found that PMEPA1 mRNA expression is upregulated in human HCC samples, and its level correlates with TGFβ1, TGFβ2, and TGFβ3 mRNA expression in TCGA liver cancer samples." (PMID 33608500, 2021). "TGFβ1, which is involved in various stages of liver disease progression, plays a significant role in initial liver injury, liver inflammation, fibrosis and liver cancer." (PMID 33707345, 2021). "In addition, from the PPI sub-network of the genes adjacent to the aberrant DNA methylation sites, we found that among the key genes with a gene node degree greater or equal to 10, MYC, EIF4E, CDK4 and TGFB1 could stimulate the pathogenesis of liver cancer." (PMID 26046465, 2015). "XPO4 and TGFβ1 may serve as useful markers to evaluate the size and prognosis of liver cancer." (PMID 23251252, 2013). "Strikingly, the TGFB1 signaling, WNT signaling, and liver cancer metastasis pathways were specifically enriched in C1QC+ TAMs, suggesting that the cells play a protumorigenic and prometastatic role in HCC." (PMID 37383234, 2023). "In our previous work, we proved that cytokines such as transforming growth factor-beta 1 (TGF-β1), tumour necrosis factor-alpha (TNF-α) and epidermal growth factor (EGF) induce the EMT of liver cancer cells in vitro." (PMID 38067256, 2023). "The present study showed that pinealectomy or exposure to constant light resulted in a significant increase in AFP, CD44, TGFβ-1, and VEGF levels indicating early development and progression of hepatic cancer cells." (PMID 35419691, 2022). "HILPDA expression was positively correlated with TGFB1 and CD274 expression in liver cancer tissues." (PMID 33816230, 2021).
liver cancer (continued). "TM4SF5-positive liver cancer cells show reduced expression of IL6, and TM4SF5 is induced by TGFβ1-mediated signaling." (PMID 29137358, 2017). "All the results above provide new insights into better understanding biological indicators, such as XPO4, TGFβ1, ANGPTL4 and elF5A2, in the prediction and evaluation of liver cancer, as well as signaling pathways in the control of liver cancer." (PMID 23251252, 2013). "IGF2BP3, an m6A reader, facilitates macrophage infiltration and M2 polarization by upregulating the expression of CCL5 and transforming growth factor beta 1 (TGF‐β1), which, in turn, inhibits CD8+ T cell activation and contributes to the progression of liver cancer." (PMID 39802639, 2025). "Furthermore, the similar results were found in another human liver cancer cells, SMMC-7721, when transfected with miR-122 or miR-122 together with TGFβ1." (PMID 26987776, 2016). "In the present study, we employed multiple techniques, including the use of qPCR, immunostaining and TMAs, as well as histology and pathology analysis, to undertake a study to evaluate XPO4, TGFβ1, ANGPTL4 and elF5A2 in carcinoma and paracarcinoma tissues from 280 liver cancer patients." (PMID 23251252, 2013). "Moreover, expression of TGFB2, but not TGFB1 was increased by BTC in vitro, repressed by DHA in both prevention and treatment mouse studies, and increased in human liver cancer meta‐analysis." (PMID 37859621, 2023).
chronic kidney disease (262 papers, 2005 to 2026). Impairment of the renal function secondary to chronic kidney damage persisting for three or more months. "Pro-fibrotic marker TGFβ1 that activates epithelial–to mesenchymal transition has been associated with chronic kidney diseases by activating pro fibrotic gene expression." (PMID 34233296, 2021). "TGFB1 Tyr81His polymorphism is a functional SNP in the Exon 2 of TGFB1 gene and has been previously studied in Asian Indians with chronic renal insufficiency." (PMID 19357773, 2009). "Instead, in renal fibrosis, a common feature of diabetic nephropathy, TGFβ1 activation and ROS accumulation support EMT-dependent fibrosis, which results in loss of function and onset of chronic kidney disease (CKD)." (PMID 39769005, 2024). "As a growth factor centrally involved in chronic fibrogenesis in most organ systems, TGFβ1 plays a key role in the development and progression of chronic kidney diseases, including DKD21." (PMID 37758806, 2023). "In the present study, we demonstrate that Tgfβ-1 gene expression is increased in the kidney removed from mice with established chronic kidney disease administered contrast compared to controls." (PMID 29700311, 2018). "Plasma levels of TGFβ1 in hypertension and end-stage renal disease are higher in African Americans, and higher levels of TGFβ1 have been reported in normotensive African Americans than in normotensive European Americans." (PMID 26540410, 2015). "Transforming growth factor β1 (TGFβ1) is a potent stimulator of epithelial-to-mesenchymal transition (EMT) and has been associated with chronic kidney diseases by activating profibrotic gene expression." (PMID 24691097, 2014). "Elevated TGFβ1 levels are also frequently observed in patients with chronic kidney disease." (PMID 39416879, 2024). "TGFβ1 is a major profibrotic mediator in chronic kidney disease (CKD)." (PMID 36717814, 2023). "Moreover, it is upregulated by TGFβ-1 in chronic renal tubular disease and involved in the progression of chronic renal disease to end-stage renal disease." (PMID 34211612, 2021). "Transforming growth factor-beta 1 (TGF-β1) plays a central role in the progression of chronic kidney disease (CKD)." (PMID 35324842, 2022). "reduced expression of transforming growth factor beta 1 (TGF-β1), connective tissue growth factor (CTGF), and α-SMA in rats, possibly by preventing the declination of L-carnitine and L-acetylcarnitine in plasma of chronic renal failure rats." (PMID 33679399, 2021). "Increased P311 expression can also be detected in tubular epithelial cells from patients with chronic kidney disease, colocalized and correlated with TGFβ1, while healthy kidney tissue does not express either P311 or TGFβ1." (PMID 30369881, 2018). "It is not unlikely that similarly to how ANGPTL2 and TGFβ1 positively increase the expression of each other in chronic kidney disease, ANGPTL4 and TGFβ1 employ such reciprocal effects on each other expression." (PMID 29100268, 2017). "Collectively, these results indicate that the KEAP1-NRF2 antioxidant system can be an effective modulator of TGFβ1-stimulated renal epithelial transition to fibroblastic cells through the SMUR1-SMAD7 signaling, and further implies the beneficial role of NRF2 in chronic renal diseases." (PMID 24691097, 2014). "Pro-fibrotic effects initiated by MBG may also be TGFβ1/SMAD-dependent and underlie vascular fibrosis in salt-induced normotensive and hypertensive rats, but TGFβ sensitive mechanisms are not involved in preeclampsia or chronic renal failure." (PMID 39295945, 2024).
Hypertension (257 papers, 2008 to 2026). The presence of chronic increased pressure in the systemic arterial system. "It is, hence, also possible, that GAs interaction with TGFB1 influences other reported adverse effects such as the increased risk of hypertension." (PMID 28829817, 2017). "TGFB1 rs1800469 polymorphism was observed to be associated with IA through co-modifying factors such as hypertension and gender." (PMID 26198819, 2015). "An association between the TGFB1+868 SNP and hypertension has been demonstrated in RA, and we have reported an association of this SNP with mortality in RA." (PMID 22513132, 2012). "Our data suggest that T29C TGFβ1 gene polymorphism was associated with clinical characteristics adequate to recognize a subset of LVH hypertensives with a higher severity of hypertension." (PMID 20981300, 2010). "Eight single nucleotide polymorphism (SNPs) have been described in TGFβ1 gene and related to its production and to hypertension and cardiovascular disease." (PMID 20981300, 2010). "Furthermore, a recent review indicated that there is a correlation between the serum TGFβ1 levels, polymorphisms of the TGFβ1 gene, and the severity of hypertension." (PMID 37201134, 2023). "In addition, we have observed an association between TGFB1, which has prognostic values for remodeling and hypertrophy in patients with hypertension and aortic stenosis, and LV function." (PMID 22136666, 2011). "Furthermore, co-modifying factors such as hypertension and sex have been associated with the TGFB1 rs1800469 polymorphism, which may exacerbate brain aneurysms by promoting vascular ECM degradation." (PMID 40563991, 2025). "ROS signaling is critical to TGFβ1-induced renal tubular EMT in renal inflammation/fibrosis in angiotensin II-induced hypertension." (PMID 32655758, 2020). "AgII, a vasoactive peptide, is a key regulator of hypertension, inflammatory response, hypertrophy, and fibrosis through the regulation of multiple signaling pathways, such as NF-κB and TGFβ1/Smad." (PMID 33117805, 2020). "This predicted activation was accompanied by transcriptional up‐regulation of TGFβ1 and TGFβ2 upon DS‐induced hypertension." (PMID 31368189, 2019). "ER stress through the activation of NFkβ and transforming growth factor beta 1 (TGFβ-1), contribute to an increase in ROS generation, which also culminates in vascular dysfunction and development of hypertension." (PMID 28562691, 2017). "Meanwhile, excessive cardiac NADPH oxidase activity in rats with high blood pressure was reported to be suppressed by TGFβ1 signalling inhibition." (PMID 29206854, 2017). "The aim of this study was to investigate the relationship between T29C TGFβ1 gene polymorphism (rs1800470), LVH and clinical severity of hypertension." (PMID 20981300, 2010). "The possibility that up-regulation of TGFβ1 gene expression in RPTCs and its downstream targets Fn1 and Col 1α, leading to higher tubulointerstitial fibrosis that facilitates the development of hypertension has received considerable attention." (PMID 31040360, 2019). "In addition, TGFB1 expression was also reported to be increased in patients with hypertension." (PMID 28829817, 2017). "Inflammation, renin-angiotensin system-sympathetic nervous system activation and insulin resistance, endothelial dysfunction Shared genes among hypertension, NAFLD, fibrosis, and inflammation include LEP, ADIPOQ, AHR and TGFB1." (PMID 37664266, 2023). "Expression of IL-10, IL-8, IL-1β, IL-6, IL-4, TGFβ1, TNFα and GM-CSF significantly decreased in the CSWT group compared with the hypertension group." (PMID 36362064, 2022). "Similarly, the ECM accumulation was evaluated using western blot, and C. cicadae downregulated the TGFβ1, α-SMA, FN, and Col-1 expression and protected the hypertension-injured kidney tissue from progressive fibrosis." (PMID 35222012, 2021).
Hypertension (continued). "This intersection analysis showed that the final list of shared genes among hypertension, NAFLD, fibrosis and inflammation contained only four genes, including LEP, ADIPOQ, AHR and TGFB1, which could be regarded as important genes related to hypertension and NAFLD." (PMID 34096467, 2021). "Furthermore, these genes and proteins, along with TGFB1 and VEGFA, demonstrated significant differences between individuals with and without hypertension." (PMID 41009355, 2025).